AR (androgen receptor)
Diseases named in the same sentence as AR in open-access papers (continued):
Sharing a sentence is not in itself a finding about the gene and the disease.
tumor (continued). "Our in vivo studies further affirms that AR is the prime target of VNPP433-3β in AR-overexpressing CRPC tumor xenografts as indicated by the remarkable reduction in levels of AR in excised tumors and concomitant tumor inhibition." (PMID 36078112, 2022). "After confirming that AR-CS can reduce proliferation and migration of SW620 cells by inhibiting Wnt5/β-Catenin, we further verified the effect of AR decoction on tumor growth in vivo." (PMID 34991661, 2022). "AR was stained in 70% of tumor nuclei and PSA was positive in about 30% of tumor cells, whereas neuroendocrine markers were not stained." (PMID 35725469, 2022). "The first gene, CLDN8, is associated with a favorable prognosis in BCa when it is co-expressed with AR, suggesting that CLDN8 acts as a tumor-suppressor gene." (PMID 35568821, 2022). "The tumor cell proliferation (fraction of Ki67+ cells), PSA staining score, and AR staining score in the primary tumors were correlated to those of paired metastases samples from the same patient." (PMID 36358614, 2022). "AR-induced DNAPK activation promotes transcriptional networks that lead to cell migration and metastasis, thus linking the AR-DNA repair axis to tumour progression." (PMID 36010882, 2022). "Inhibition of AR-mediated transactivation by ADT and antiandrogens results in tumor-growth inhibition until therapy resistance occurs." (PMID 34667276, 2022). "Alteration of genes that are associated with a higher 18F-FDG uptake, correlated positively with higher glucose uptake in both AR and PSMA suppressed tumours." (PMID 35741197, 2022). "A single dose of PROTAC 10 also effectively reduced AR and PSA proteins in VCaP xenograft tumour tissues in mice for more than 48 h." (PMID 35702041, 2022). "Combined inhibition targeting both the AR and JAK2/STAT1 resulted in substantial tumor suppression due to the reduction in DNA damage repair ability and increment in apoptosis." (PMID 34746227, 2021). "We did not observe any statistically significant correlations between AR and TERT abundance, or tumour TL." (PMID 34824250, 2021). "Through a systems medicine approach, it was determined that hub biomolecules, AR, GATA2, miR-124, TOR1AIP1, ESR1, EGFR, STAT1, miR-192, GATA3, COL1A1, in tumor microenvironment generic network." (PMID 33907495, 2021). "AR mRNA expression was significantly higher in NMIBC compared with MIBC tissues, and a trend towards lower AR expression and tumour stage was observed." (PMID 33797847, 2021). "Additionally, in the state of mCRPC, it has been demonstrated that tumor proliferation and spreading is still driven by AR, through several and still not fully understood mechanisms, among whom AR gene amplification, entailing an overexpression of AR, has been found in 30% to 50% of CRPC patients." (PMID 33809749, 2021). "FOXA1 co-regulates an AR-mediated transcriptional program in healthy prostate and in primary tumours via making response elements (ARE) accessible to AR and/or by direct interaction with AR itself." (PMID 34940756, 2021). "This current study shows that AC016745.3 can function as a tumor-suppressor in PCa, and that increased AC016745.3 expression inhibits AR-dependent gene transcription in LNCaP cells." (PMID 34833084, 2021). "Upon androgen deprivation therapy or AR blockade, the PSMA level rises in the tumor tissue and its metastases at the cellular level, thus enabling therapeutic targeting as well as detection by PSMA-based imaging." (PMID 34298770, 2021). "Overall, these studies demonstrate androgen-induced tumor regression in PDX models and thus provide a preclinical foundation for stimulating AR function to treat ER-positive breast cancer." (PMID 34680352, 2021). "The inflammatory cytokine IL-23 is produced by MDSCs and has been recently linked to CRPC development, since it induces the transcription of AR target genes through STAT3-RORγ pathway, leading to the proliferation of cancer cells and tumor progression." (PMID 35011582, 2021).
tumor (continued). "The mRNA levels of TEK, BMP1, AR, SLC11A1, SLC40A1, and F2RL1 were significantly downregulated in tumor cells compared with normal cells, and CX3CL1 and RNASE2 were upregulated in tumor cells." (PMID 35004689, 2021). "Exosomal miR-224-5p derived from tumor cells significantly promoted the growth and metastasis of NSCLC by inhibiting AR expression." (PMID 34718336, 2021). "The correlations between AR expression and disease characteristics, such as age, FIGO tumor stages, differentiated grades, and the serum level of CA125 were also evaluated in this study." (PMID 33613770, 2021). "The majority of AR+ tumours (85.7%) was LDBC subtype, with median percentage of TILs was 37.5% and 10% in AR− and AR+ tumours, respectively, (p = 0.10)." (PMID 35047068, 2021). "Our findings suggest that many of patients who had elevated expression of tumor‐specific signatures such as ESR1, AR, VEGF, AKT1/2/3, CCND1, CDK1, and MMP9 had significantly poorer disease‐free survivals compared with the remaining subgroups." (PMID 33275817, 2021). "Top upregulated master regulators in the tumor, as compared to the parent cells, include ZEB2 and PHLDA1; while top downregulated master regulators include AR, AHR, and ITGA6." (PMID 33808801, 2021). "Our studies reveal a unique oncogenic role of stress responsive protein G3BP1 that negatively regulates tumor-suppressive SPOP ubiquitin ligase, leading to upregulation of AR signaling and prostate tumorigenesis." (PMID 34795264, 2021). "Differential responses to AR-blockers in LAPC9 and BM18/PNPCa organoids suggests that drug response correlates with individual tumor phenotypes." (PMID 33602919, 2021). "The expression levels of AR, CAT, CYP3A4, ESR1 and SLC10A1 were markedly upregulated in primary tumour tissues compared with normal tissues." (PMID 34717619, 2021). "Further, A485 inhibited tumor growth in castration-resistant PCa xenograft models; it also led to a decrease in the mRNA levels of MYC and the AR-dependent gene SLC45A3, and a reduction in MYC protein levels." (PMID 33803759, 2021). "In multivariate analysis of men receiving ADT, only two factors were significant, UBC AR expression and UBC tumor number (single vs. multiple)." (PMID 34768683, 2021). "The ACACA, AR, MAPK, PDK1, PEA15, and SYK showed significant differential expression between normal tissues and tumor tissues (P < 0.0001)." (PMID 33842538, 2021). "Further characterization using Pearson correlation analyses did show positive correlations between tumor burden, p-AKTpS473, p-PRAS40 and aberrant AR." (PMID 34439133, 2021). "Compared to the parent LNCaP cells, expression of AR, AHR, CDH1, CXCR7, FLNA, ITGA6, and UGT2B15 in tumor was significantly inhibited." (PMID 33808801, 2021). "In order to find the mechanism by which XIST regulates AR protein expression, a relation between miR-124 and XIST was observed; miR-124 has recently been confirmed as a tumor suppressor regulating proliferation, migration, and invasion in many cancers." (PMID 33919565, 2021). "Targeting both the AR and PI3K pathway was tested in a randomised controlled trial, and demonstrated durable responses in PTEN-null tumours when treated with abiraterone and the Akt-inhibitor ipatasertib." (PMID 33808193, 2021). "A recent study in PgR-low/null tumors defined phospho-PgR target gene sets (ERBB2, PAX2, AHR, AR, and RUNX2) which regulate cancer stem cell biology and increase tumor heterogeneity." (PMID 34638241, 2021). "It is a new androgen receptor co-inhibitor and exerts its tumor suppressor function by recruiting histone deacetylases, indicating that the CMTM1 gene is a potential tumor suppressor gene." (PMID 33585698, 2021). "Targeting AR with its degradation enhancer, in RCC preclinical models, they obtained a suppression of RCC tumor progression." (PMID 34572815, 2021). "The influence of AR expression on prognosis is still being controversial, as the role of AR signaling in TNBC tumor cells is still not well understood." (PMID 33915941, 2021).
tumor (continued). "TFs mutated only in CRPC typically had lower expression in CRPC, with the exception of AR and EHMT1, a histone methyltransferase with potential tumor suppressive function in the prostate." (PMID 34283056, 2021). "Known exceptions that can be considered driver events include promoter and enhancer rearrangements such as known for AR and FOXP1, but also tumour suppressor gene deletions." (PMID 34891161, 2021). "Lastly, FKBP51, an AR-dependent gene and a positive regulator of AR activity, is highly expressed in castrate resistant PCa (CRPC) when compared with primary tumours." (PMID 34064250, 2021). "Androgen-independent growth of tumor cells can be mediated by the hormone RLN2, which can activate the AR signaling pathway by inducing the formation of the β-catenin–AR complex and its translocation to the nucleus." (PMID 34440475, 2021). "In contrast, both prostate-related (AR and KLK3) and tumor-derived (PCA3 and PSMA) genes were successfully detected in 780 LNCaP or 22Rv1 and 78 22Rv1 cells." (PMID 34771706, 2021). "To verify the clinical relevance of AR overexpression in CRPC cell models, we assessed AR expression by IHC in 12 tumor samples from men with progressive disease in the face of ADT." (PMID 34575033, 2021). "Surprisingly, clusters with the strongest oncogenic and tumour suppressor potential share five regulatory regions (MAX, ERG, EP300, AR and MYC)." (PMID 34198662, 2021). "Reduced AR transcriptional activity of tumor is a feature of AVPC, often reflecting by relative low PSA and can predict AR signaling inhibitor (ARI) resistance." (PMID 33903734, 2021). "Expression status of two AR target genes, PSA and PSMA, in CaP circulating tumor cells, were used as a measure of AR activity and correlated with CaP response to ADT." (PMID 34439101, 2021). "Other reports described reduced LN metastases in AR+ TNBCs, or just similar clinico-pathologic profile between AR+ and AR− TNBC tumours." (PMID 35047068, 2021). "From 41 mCRPC patients (including 31 treated with Androgen Receptor Signaling Inhibitors [ARSI]), Circulating Tumor Cells (CTCs) were prospectively enriched with AdnaTest platform and analyzed with a multiplexed assay for HER2 and AR-V7 mRNA expression." (PMID 34885125, 2021). "Cryptotanshinone, a natural compound isolated from S. miltiorrhiza, modulates androgen receptor (AR) transcriptional regulation and downregulates TMPRSS2 gene expression as an AR target gene in androgen-responsive tumor cells." (PMID 34122058, 2021). "An AR degradation enhancer, dimethylcurcumin (ASC-J9), has also demonstrated effective tumor inhibition, including against OVCA." (PMID 34299364, 2021). "We discovered that AD and AR downregulated TRF2 and exhibited anti-tumorigenic activity specific for tumor cells overexpressing TRF2." (PMID 34203903, 2021). "In this study, miR-181 promoted cells proliferation and tumor growth in mice via targeting DAX-1, a negative regulator of androgen receptor in PC." (PMID 33331954, 2021). "Two well-established PC markers, PSA and AR, were found to maintain the same expression level in D17225 PDX tumors that in the primary tumor." (PMID 32092044, 2020). "In addition, AR was demonstrated to be a novel target of maspin which may reflect an additional characteristic of maspin for its anti-tumor activity and enriched its anti-tumor potency." (PMID 33195208, 2020). "Important to note is that the expression of androgen receptor (AR), also in CRPC and metastatic CRPC (mCRPC), is a key factor for tumor proliferation." (PMID 32650419, 2020). "Curcumin also downregulated the expression of the AR protein and NKX3.1 tumor suppressor, as well as PSA levels, Erb-B2 Receptor Tyrosine Kinase 2 (ERBB2), and epidermal growth factor receptor (EGFR)." (PMID 33182828, 2020). "Immunohistochemical staining revealed the tumour cells to be AE1/AE3, CK7, GCDFP-15, E-cadherin, androgen receptor stain and GATA3 positive." (PMID 33054772, 2020).
tumor (continued). "Further analysis showed that most CNAs, including amplification in AR and deletion in PTEN in P8, amplifications in ELF2 and MYC in P9, and amplifications in MYC and CCND1 in P11, were concordant in the plasma and tumor tissues." (PMID 32631448, 2020). "Testosterone-induced strong AR-pathway stimulation, as shown by AR nuclear localisation and target gene expression, which led to rapid outgrowth in five out of seven PC346C-DCC-K tumours." (PMID 32989230, 2020). "In support to a possible correlation between miR-9-5p and AR, we further reported an inverse correlation between miR-9-5p and AR expression in a set of paired FFPE tumor and adjacent non-tumor BC patients." (PMID 33282861, 2020). "There were significant correlations between PSA and PSMA mRNA expression, as well as tumor volumes (both MTV and TTV), AR-FL and AR-V7 mRNA expression." (PMID 32685010, 2020). "AR amplifications can be detected by fluorescence in situ hybridization (FISH), either on tissue or on circulating tumor cells (CTCs)." (PMID 33321757, 2020). "Consistent with the elevated AR signaling observed in BCN1371, this tumor exhibits histologic features of an apocrine cancer with intensely eosinophilic cytoplasm and AR expression." (PMID 31988290, 2020). "The pro-survival role of AR in TNBC is further supported by in vitro studies where AR signaling yielded a proliferative effect and a CSC-like state in AR+ TNBC cell lines, thus facilitating tumor stemness." (PMID 32850312, 2020). "The widespread clinical use of more potent androgen receptor pathway inhibitor drugs, such as ENZ, to treat CRPC tumours has increased the emergence of more aggressive tumour types such as the NEPC." (PMID 32802517, 2020). "In contrast, virtually all CDX tumor cells expressed neuron-specific enolase (NSE), chromogranin A, Ki67, and CD44 evidencing emergence of an AR-null, neuroendocrine-positive phenotype." (PMID 32313004, 2020). "CTCs were characterized by mRNA in situ padlock probe analysis which visualizes AR-V7, AR full length (AR-FL), and kallikrein-related peptidase 3 (KLK3, often referred to as prostate specific antigen (PSA)) transcripts directly in tumor cells." (PMID 32796730, 2020). "Four of five members tested from this library suppressed AR protein expression (GSA0932> GSA1512> GSA1504> GSA1508) in androgen-dependent (LNCaP) and CRPC tumor cells (C2-4) after a 24h treatment at 10 μM." (PMID 32477465, 2020). "Immunohistochemical staining revealed the tumour cells to be AE1/AE3, CK7, GCDFP-15, E-cadherin, androgen receptor (AR) stain and GATA3 positive." (PMID 33054772, 2020). "A clinical trial was conducted by Scher and colleagues to assess the anti-tumour activity and safety of MDV3100 (or enzalutamide, an AR antagonist that inhibits androgen-AR binding) in men with CRPC." (PMID 33303035, 2020). "Similar effects were observed in an in vivo AR+ TNBC xenograft model where there was a significant reduction in tumor volume and a delay to tumor doubling and tripling times in mice treated with seviteronel and radiation." (PMID 32117061, 2020). "The more aggressive tumours like TNBC require other targets for their treatment such as inhibitors of immune checkpoints, platinum compounds, PARP or PI3K inhibitors, and even androgen receptor inhibitors." (PMID 32872155, 2020). "Naa10p was recently demonstrated to be a downstream target gene of the androgen-AR axis and functions as a tumor promoter in ADPC through interacting and acetylating the AR and activating AR-mediated gene expressions such as of PSA18." (PMID 32719332, 2020). "We found that TLR4 and AR were expressed more highly in HCC tumor tissue than in adjacent liver tissue, and we found that the expression of TLR4 was positively correlated with AR in HCC tumors (R=0.6348, P=0.026)." (PMID 31956356, 2020).
tumor (continued). "A number of studies suggest a bidirectional interaction between AR and PPAR, with each receptor influencing the expression and/or activity of the other within prostatic tissues or tumor cells." (PMID 33031638, 2020). "When using an AR cut-off value of 25%, the mean UGT2B17 nuclear expression is 38% (95% CI: 29–46) vs 57% (95% CI: 50–64) in the AR < 25% vs AR ≥ 25% tumours, respectively (P = 0.0003)." (PMID 32047296, 2020). "For primary tumor tissue (n = 23), the SRD5A1 expression levels and AR pathway activity scores were higher in patients with clinical benefit, but significance was lost (p = 0.57 and p = 0.20, respectively)." (PMID 31745978, 2020). "Curcumin also inhibits tumour growth and suppresses the PSA levels which stimulated by the activation of AR and interleukin-6 in ADPC (LNCaP) cells." (PMID 32131560, 2020). "Differences in tumor biology between QNBC and TNBC can be exploited to yield novel therapies for targeted management of AR-negative and AR-positive TNBCs." (PMID 33213491, 2020). "For instance in prostate-derived LNCaP tumor cells, DHEA acts at the androgen receptor (AR) and beta estrogen receptor beta (ER-beta) at similar affinities, but the effects at ER-beta appear to be more physiologically relevant." (PMID 32194506, 2020). "Tumours formed by the DVL3 model maintained the heterogeneous CK8+/CK5+ glandular structures and regions of AR positivity, similar to the tumours from which they were derived." (PMID 33003551, 2020). "Since it is also essential in immune cells, we studied whether the expression of AR full-length (ARFL) and its splicing variant ARV7 in peripheral blood mononuclear cells (PBMC) predicts systemic treatment response in mCRPC in comparison with circulating-tumor cells (CTC)." (PMID 31947623, 2020). "The inhibition of both AR (with enzalutamide) and CLU (with OGX-011) synergistically increased apoptotic rates and delayed the appearance of CRPC in LNCaP tumour and PSA progression in vivo." (PMID 35582226, 2020). "Previous data have indicated that androgen receptor (AR) and phosphoinositide-3 kinase (PI3K) are upregulated and become dominant pathways in tumor tissues with aging." (PMID 32148477, 2020). "Immunohistochemical assessment of AR, ER, PR, Ki67 and HER2 were performed using tissue microarrays (TMA) constructed from their primary tumor block." (PMID 32374753, 2020). "Nevertheless, these findings are consistent with the conclusion that AR expression is negatively correlated with ASS1 expression, thus contributing to RCC tumor progression, likely by regulating the ceRNA activity of ASS1 pseudogenes." (PMID 31000693, 2019). "Both AR and FOXA1 were strong and favorable prognostic factors, independently of tumor stage at diagnosis." (PMID 31888566, 2019). "Androgen receptor and PKM2 are both engines for PCa growth, as the former regulates cell cycle, and the latter, tumor metabolism." (PMID 30072740, 2019). "In the present study, we describe a novel lysine demethylase which interacts with both AR and PKM2 to reprogram androgen responses and tumor metabolism." (PMID 30072740, 2019). "With the goal of assessing the clinical significance of accounting for the variables selected by our method, the genes selected by EN and twiner were tested in a survival analysis using the Cox regression model on ER+ BRCA, AR+ TNBC and PRAD tumor data." (PMID 31238876, 2019). "The epithelium cells of the tumor were also positive for AR and NKX3.1 staining, indicating that the tumor originated from the prostate." (PMID 30808350, 2019). "Analysis of ChIP sequencing data (GSE56288) for the recruitment of HOXB13 and AR to the vicinity of the CIT/STK21 revealed overlapping peaks, consistent with our original selection for tumor-specific ARBS." (PMID 31273254, 2019).